APP (amyloid beta precursor protein)
Diseases named in the same sentence as APP in open-access papers (continued):
Sharing a sentence is not in itself a finding about the gene and the disease.
Stroke (55 papers, 2009 to 2025). Sudden impairment of blood flow to a part of the brain due to occlusion or rupture of an artery to the brain. "On the one hand, a violation of the blood–brain barrier during a stroke can cause an increase in APP and Aβ in the blood and their accumulation in the tissues of peripheral organs, disrupting metabolism." (PMID 36289917, 2022). "Macrohemorrhages were overall observed in 2 APP mutation carriers, both with CMHs and history of stroke." (PMID 33495373, 2021). "Our work in rats demonstrates that although TSPO detected neuroinflammation near the ET1-induced infarct, only MHCII was able to detect the WM microglial activation that occurred late post-stroke or in response to overexpression of pathogenic APP." (PMID 32990808, 2020). "Histochemical studies identified significant changes in APP in the infarcted area (closely associated with glial cells) and tests for Aβ1-42- which has been previously reported to increase, not only in stroke, but also in other neurodegenerative disorders." (PMID 30283295, 2018). "Since a remarkable amount of APP is eliminated through the glymphatic pathway, impaired glymphatic clearance could be implicated in the development and progression of stroke." (PMID 36278004, 2022). "This leads to an increase of amyloidogenic APP processing, which may contribute to the pathogenic interaction between hypertension, stroke, and AD." (PMID 31776837, 2020). "We review recent epidemiological data on stroke (including haemorrhagic stroke) in order to make comparisons with a rare form of familial AD due to duplication (i.e. having three copies) of theAPP region on chromosome 21, here called ‘dup-APP’, which is associated with more frequent and severe ICH." (PMID 27239286, 2016). "In the Morris water maze, performed 8 months post-surgery at 12 months of age, we tested spatial learning and hippocampal-dependent memory in both male and female, sham- or stroke-induced APP/PS1 and WT mice." (PMID 40141679, 2025). "At 0.5 months post-stroke induction, female APP/PS1 mice showed lower CBF than male APP/PS1 mice (indicated with c), and 4 months after surgery, female WT had lower CBF than male WT mice (indicated with b)." (PMID 40141679, 2025). "In the light phase, overall sex, genotype, and surgery effects were detected: female mice walked more than males, stroke-operated mice walked more than sham-operated mice, and APP/PS1 mice walked more than WT mice." (PMID 40141679, 2025). "Here, female stroke-operated WT and female sham-operated APP/PS1 mice demonstrated lower dispersion levels than their male counterparts, implying better myelin quality among male animals." (PMID 40141679, 2025). "Neuroinflammation was evaluated post-mortem via immunohistochemistry in male and female, sham- or stroke-operated WT and APP/PS1 mice, 8 months post-surgery at 12 months of age." (PMID 40141679, 2025). "It was assessed in immunohistochemically stained samples using the WO-2 antibody in male and female, sham- or stroke-operated WT and APP/PS1 mice, 8 months post-surgery at 12 months of age." (PMID 40141679, 2025). "Four months after surgery, APP/PS1 sham mice showed lower FA than WT sham animals, while stroke-operated APP/PS1 animals displayed higher FA than APP/PS1 sham mice." (PMID 40141679, 2025). "Among stroke mice, APP/PS1 animals had significantly less activated microglia and a smaller IBA-1+ area in the thalamus compared to WT mice." (PMID 40141679, 2025). "In summarizing this study, we affirm that our risk assessment model, based on PADGs, specifically APP, THBS1, F13A1, SRC, PPBP, and VCL, presents robust diagnostic capabilities for stroke patients." (PMID 38268925, 2023). "tMCAO rats are considered suitable for preclinical stroke research, while the APP/PS1 mice model is used for AD research." (PMID 37893101, 2023).
Stroke (continued). "Because of the small amount of information on the family of amyloid-like proteins and their role in stroke, similarly as in the case of APP, further research is necessary to establish their exact role in this group of patients." (PMID 35268287, 2022). "The accumulation of APP in damaged neurons after ischemic stroke indicates its important role in stroke-induced pathological processes in the nerve tissue." (PMID 36289917, 2022). "When acute (stroke and cardiac arrest) or chronic (cerebrovascular disease) hypoxic-ischemic disease occurs, APP will be upregulated." (PMID 35097126, 2022). "In this study, we investigated the expression and localization of APP in rat brain cells after photothrombotic stroke (PTS)." (PMID 36289917, 2022). "APP carriers tend to have a notable level of amyloid angiopathy in their brain, which can lead to cerebral hemorrhage and stroke (i.e., in carriers of APP duplications)." (PMID 33464407, 2021). "When investigating this, we observed that stroke induced disturbances in the expression levels of the APP and BACE mRNA and that LOPC restored these levels." (PMID 33841293, 2021). "Stroke animals exhibited a significant decrease in the expression of APP and BACE mRNA levels relative to sham animals (F = 16.56, p < 0.001 and F = 4.61, p < 0.05, respectively)." (PMID 33841293, 2021). "For instance, mutant mice overexpressing APP exhibited a substantial reduction of cerebral blood flow (CBF) accompanied by larger infarcts after stroke, suggesting that APP exacerbated ischemic injury by impairing structural and functional vascular integrity." (PMID 34566627, 2021). "In contrast, APP was present throughout the narrow zone of neural tissue damage induced by DCHK and APP accumulation was prominent in damaged axon bundles close to DCHK deposits in a manner comparable with L-NIO stroke lesions." (PMID 33277474, 2020). "Milner and collaborators have described that young APP mice, as compared to control mice, have a 46% larger infarct volume after experimental stroke, which is exacerbated with aging (85 ± 9 mm3 in APP mice vs. 46 ± 9 mm3 in control, p < 0.05)." (PMID 31776837, 2020). "Novel findings on APP-related neuroprotective mechanisms open promising new therapeutic strategies in stroke, AD and TBI." (PMID 28210211, 2017). "A key observation is the up-regulation of APP following acute (stroke, cardiac arrest) or chronic (cerebrovascular disease) hypoxic-ischemic conditions." (PMID 28210211, 2017). "In that study, lower levels of CSF APP metabolites in the stroke group compared to the SCD/MCI-group suggested that ischemia influences APP metabolism, probably through inhibition of fast axonal transport of APP." (PMID 26856756, 2016). "This explains the finding of AD-like pattern in rodents, starting some days after ischemia—an increase of 200 % of APP in the penumbra on the seventh day post-stroke is described up to 1 year after the event." (PMID 23877436, 2013). "An inverse relationship was demonstrated between the volume of chronic WML and CSF APP metabolites (sAPP-α, sAPP-β, Aβ X-38, X-40 and X-42) in both stroke patients and SCI/MCI patients." (PMID 20673341, 2010). "Experimental stroke and ischemia lead to an increased production of APP, upregulation of β-secretase activity, and an accumulation of Aβ peptides and APP around ischemic WMLs." (PMID 20673341, 2010). "Notably, stroke-operated APP/PS1 mice exhibited a lower amount of microglia than their sham-operated counterparts." (PMID 40141679, 2025). "In addition to the stroke effect, we also found that in females, the APP/PS1 group had a larger contralateral hippocampal volume than WT mice." (PMID 40141679, 2025). "Additionally, APP/PS1 stroke mice exhibited lower FA in the contralateral cortex compared to WT stroke mice (indicated with i)." (PMID 40141679, 2025).
Stroke (continued). "Noteworthy, stroke may accelerate Aβ accumulation and WM lesions by interfering with clearance pathways, explaining the very early WM degeneration in APP/PS1 mice." (PMID 40141679, 2025). "Interestingly, at 7 weeks post-stroke, amyloid precursor protein (APP) was over-expressed, mainly by microglial cells, and adopted a plaque-like morphology, with iron accumulation around the plaques, indicative of neurodegeneration." (PMID 34884906, 2021). "Moreover, the administration of MCS-derived extracellular vesicles mitigated the aggregated inflammatory responses in the acute stage of stroke and alleviated the trained-immunity-induced increased load of amyloid-β in APP/PS1 mice." (PMID 33330429, 2020). "Despite a family history of stroke in this patient, genetic studies did not reveal any pathogenic mutations in the APP, PSEN1 or PSEN2 genes." (PMID 29450646, 2018). "However, to date no clear evidence exists that confirmed the correlation of AD and stroke leading to declined cognitive function in APP transgenic mice and patients." (PMID 24587388, 2014). "A cohort survey was performed to examine whether SVD or acute CVD affects APP metabolism and to explore a potential association between WML and APP metabolism in two groups; cognitively impaired patients, subjective and mild (SCI and MCI) and stroke patients." (PMID 20673341, 2010). "During day and night, APP/PS1 mice displayed increased locomotion compared to WT mice, while stroke-induced animals exhibited greater locomotion than their sham counterparts." (PMID 40141679, 2025). "A body weight gain was noted in WT sham (between months: 1→2, 2→3, 3→4, 5→6, 1→8), WT stroke (between months: 1→2, 2→3, 1→8), APP/PS1 sham (between months: 1→2, 1→8), and APP/PS1 stroke mice (between months: 1→2, 2→3, 5→6, 1→8) during the post-surgery period." (PMID 40141679, 2025). "Specifically, in the contralateral thalamus, only APP/PS1 stroke mice exhibited higher CBF than APP/PS1 sham mice, and APP/PS1 sham mice had overall lower CBF in comparison to WT sham mice." (PMID 40141679, 2025). "In order to examine the common and unique MEV profiles in these disorders, aged wildtype and APP/PS1 transgenic rats were used to develop experimental models of aging, AD, stroke, and comorbid AD/stroke." (PMID 40542975, 2025). "He proposed that stroke-induced hypoxia compromises the BBB and the overexpression of APP alters the balance between Aβ production and clearance in favour of production, which induces neuroinflammation." (PMID 36440263, 2022). "Our studies reveal changes in the expression of the main participants in the processing of amyloid precursor protein (APP) in neurons and astrocytes after photothrombotic stroke (PTS)." (PMID 36289917, 2022). "Regarding the positive correlation of the expression of APP, α-secretase of ADAM10, and γ-secretase subunits of PS1 and NCT after PTS, further research to reveal the exact roles of these proteins in stroke would be interesting and valuable to explore." (PMID 36289917, 2022). "The important biological targets for network pharmacological analysis of TM-CX and TM-JH related to stroke were PTGS2, ACE, APP, NOS1, and NOS2." (PMID 32328128, 2020). "In order to investigate whether there are some common pathological links in stroke and AD, we used the suture method to block the middle cerebral artery and simulate stroke, and observed the expressions of the characteristic protein Aβ, its precursor APP and AQP4 after CIRI." (PMID 33817204, 2019). "While several evidences showed increased APP processing in cerebral regions affected by brain ischemia, so far the precise role of AICD in stroke pathophysiology and signaling cascades remains almost unexplored." (PMID 28106772, 2017). "In the future, significant proteins including UBC, CUL3, APP, NEDD8, JUP, SIRT7, etc., can be potent drug targets for first aid and emergency treatment within 24 h post-stroke." (PMID 26679092, 2015).
Stroke (continued). "Specifically, some shared PPIs such as APP - EXOC6 functions in the amyloid formation, which has been known to be involved in both stroke and myocardial infarction." (PMID 25539592, 2014). "The anti-stroke agent, pifithrin-alpha (PFTα), was a closely related benzothiazole to JTR-0013, and was previously found to be a selective APP translation inhibitor in our assays." (PMID 23935819, 2013). "Moreover, at 4 months post-stroke, thalamic CBF was lower in male APP/PS1 mice compared to male WT mice (indicated with d)." (PMID 40141679, 2025). "This stroke effect was absent in APP/PS1 mice, likely due to less constant weight gain, typical for this AD-like animal model." (PMID 40141679, 2025). "Early studies using human post-mortem brains revealed that amyloid precursor protein (APP) is not implicated exclusively in AD pathology, and its expression is as well induced in the brain after stroke." (PMID 34566627, 2021). "In contrast, APP/PS1 mice did not exhibit stroke-related weight differences with age." (PMID 40141679, 2025). "Furthermore, stroke-induced hypoxia can lead to the overexpression of amyloid precursor protein (APP) in VSMCs, which could exacerbate or expedite the development and progression of CAA, worsen stroke outcome, and lead to PSD." (PMID 36440263, 2022). "Furthermore, stroke-induced hypoxia can lead to overexpression of APP in vascular smooth muscle cells, which could expedite or exacerbate local CAA development and worsening of stroke outcome." (PMID 31776837, 2020). "Lower CSF levels of sAPP-α and sAPP-β in the stroke group than in the SCI/MCI group and an inverse correlation with chronic WML indicate that ischemia lowers the levels of CSF sAPP metabolites and suggests that APP axonal transport or metabolism may be affected in SVD of the brain." (PMID 20673341, 2010). "It is unclear how APP affects the ischemic environment, or how the lack of APP leads to acute mortality, but these observations may have implications in AD patients treated with Aβ and APP targeted therapies as strokes and ischemic episodes are frequent in the elderly population." (PMID 22912719, 2012). "The volume of acute post-stroke changes (infarct volume and surrounding WML halo) did not correlate with levels of CSF APP metabolites (data not shown)." (PMID 20673341, 2010).
breast cancer (53 papers, 2009 to 2025). A primary or metastatic malignant neoplasm involving the breast. "APP has been suggested to be oncogenic in breast cancer, which is a significant cause of morbidity and mortality among women." (PMID 34066808, 2021). "APP has been reported to be associated with androgen-responsive genes in prostate and breast cancer, and it has been suggested APP promotes malignancy." (PMID 34066808, 2021). "APP immunoreactivity has been detected in 49 percent of breast carcinoma tissues, and increases in this percentage are associated with androgen receptor in ER-positive breast carcinoma." (PMID 34066808, 2021). "On the other hand, the buildup of amyloid precursor protein (APP), the precursor of the AD hallmark amyloid beta (Aβ) peptides, have now been found in pancreatic and breast cancer tumors and the corresponding metastatic lymph nodes." (PMID 31137462, 2019). "The elevated co-expression of NGFR, EFNB1, and APP was associated with longer overall and metastasis-free survival of patients with breast cancer." (PMID 30446011, 2018). "Applying the Gene Set Analysis (GSA) we found that elevated expression of HRH1, EFNB1, KLK1, NRP2, and APP was associated with the basal-like subtypes of breast cancer as predicted by the MicMa cohort." (PMID 26673618, 2016). "Recently, increased expression of APP in several types of cancer has been reported and it has been implicated in proliferation and motility of advanced breast cancer." (PMID 27481518, 2016). "Transcripts for ZNF395 and APP (amyloid precursor protein) were identified as targets of the metastasis associated protein TARBP2 in the highly metastatic breast cancer cell line MDA-LM2." (PMID 26229239, 2015). "Knockdown of APP (APP-kd) in breast cancer cells caused the retardation of cell growth in vitro and in vivo, with both the induction of p27kip1 and caspase-3-mediated apoptosis." (PMID 25491510, 2014). "We found that the expression level of APP is mechanistically linked with tumorigenicity and malignancy of breast cancer." (PMID 25491510, 2014). "Overall, our findings provide substantial groundwork for the pathophysiological function of APP and its underlying mechanism that promotes breast cancer malignancy." (PMID 25491510, 2014). "To understand the underlying mechanism of the effect of APP on breast cancer cells, we examined the signaling pathways potentially linked to p27kip1 and apoptotic induction in APP-kd cells." (PMID 25491510, 2014). "A positive association was also observed between APP and AR in breast cancer tissues." (PMID 41614805, 2025). "Moreover, APP expression is influenced by androgen receptor activity and is associated with a poor prognosis in some breast cancer subtypes." (PMID 39123408, 2024). "APP and its processing enzymes were shown to be linked with breast cancer via Akt phosphorylation." (PMID 32391121, 2020). "Interestingly, APP depletion causes cell cycle arrest in breast cancer cells and non-small cell lung cancer." (PMID 33232279, 2020). "For example, APP promotes migration and invasion of breast cancer cells and is a predictor of poor prognosis in some breast cancers; whereas alpha-synuclein may be implicated in the malignant progression of meningioma." (PMID 33207722, 2020). "In cancers such as colorectal cancer (CRC), breast cancer (BC), and myeloproliferative neoplasms, reduced expression of calreticulin has been linked to compromised APP." (PMID 40075727, 2025). "Specifically, it has been reported that APP is linked to proliferation of thyroid epithelial cells and epidermal basal cell proliferation and, interestingly, the increased expression of APP in several types of cancers including pancreatic, lung, colon and breast cancer has been reported." (PMID 25491510, 2014). "In breast cancer cells, silencing APP reduced cell growth and it was additionally noted that there was no induction of apoptosis." (PMID 41614805, 2025).